TRAV12-1 (T cell receptor alpha variable 12-1)
Description:
V region of the variable domain of T cell receptor (TR) alpha chain that participates in the antigen recognition. Alpha-beta T cell receptors are antigen specific receptors which are essential to the immune response and are present on the cell surface of T lymphocytes. Recognize peptide-major histocompatibility (MH) (pMH) complexes that are displayed by antigen presenting cells (APC), a prerequisite for efficient T cell adaptive immunity against pathogens. Binding of alpha-beta TR to pMH complex initiates TR-CD3 clustering on the cell surface and intracellular activation of LCK that phosphorylates the ITAM motifs of CD3G, CD3D, CD3E and CD247 enabling the recruitment of ZAP70. In turn ZAP70 phosphorylates LAT, which recruits numerous signaling molecules to form the LAT signalosome. The LAT signalosome propagates signal branching to three major signaling pathways, the calcium, the mitogen-activated protein kinase (MAPK) kinase and the nuclear factor NF-kappa-B (NF-kB) pathways, leading to the mobilization of transcription factors that are critical for gene expression and essential for T cell growth and differentiation. The T cell repertoire is generated in the thymus, by V-(D)-J rearrangement. This repertoire is then shaped by intrathymic selection events to generate a peripheral T cell pool of self-MH restricted, non-autoaggressive T cells. Post-thymic interaction of alpha-beta TR with the pMH complexes shapes TR structural and functional avidity.
Synonyms: TCRAV12S1; TCRAV2S3; TRAV121
Gene: T-cell receptor variable (V) gene on chromosome 14 (21,841,240 to 21,841,774, forward strand). Ensembl gene ENSG00000211785.
Subcellular location: Cell membrane
Gene Ontology:
Molecular function: peptide antigen binding
Cellular component: plasma membrane
Homologues: Orthologues: chimpanzee TRAV12-1 (80% identical), mouse Trav7-3 (61% identical), mouse Trav7d-3 (61% identical), rat Trav12-3 (59% identical), mouse Trav7d-6 (58% identical), mouse Trav7n-6 (58% identical), mouse Trav7-6 (57% identical), mouse Trav7-1 (55% identical), mouse Trav7n-4 (55% identical), mouse Trav7d-4 (54% identical), mouse Trav7-2 (54% identical), mouse Trav7-4 (54% identical), and 4 more. Paralogues in human: TRAV12-3 (76% identical), TRAV12-2 (75% identical), TRAV23DV6 (37% identical), TRAV29DV5 (37% identical).
Diseases named in the same sentence as TRAV12-1 in open-access papers:
TRAV12-1 is named in the same sentence as 3 diseases in open-access papers, as found by Europe PMC text mining. Sharing a sentence is not in itself a finding about the gene and the disease. The quoted sentences say what the papers report.
Löfgren's syndrome (1 paper, 2020). "Using deep sequencing approaches, our group recently demonstrated that TRAV12-1 preferentially pairs with TCRβ variable region (TRBV) 2 in BAL CD4+ T cells from Löfgren's syndrome patients and that TRAV12-1 and TRBV2 are the most expanded variable regions relative to control subjects." (PMID 32256501, 2020).
sarcoidosis (1 paper, 2020). Sarcoidosis is a multisystemic disorder of unknown cause characterized by the formation of immune granulomas in involved organs. "In an acute form of sarcoidosis, there are expansions of specific TRAV12-1/TRBV2 T cell receptors expressed on BAL CD4+ T cells, indicating that these T cells are trafficking to and expanding in the lung in response to common antigens." (PMID 32256501, 2020).
TRAV12-1 also shares sentences with these, for which no sentence is quoted: COVID-19 (1 paper).